TLR3 (toll like receptor 3)
Diseases named in the same sentence as TLR3 in open-access papers (continued):
Sharing a sentence is not in itself a finding about the gene and the disease.
tumor (continued). "Moreover, NK cells were also involved in the reshaping of the tumor microenvironment into one responsive to ICB through sensitization therapy consisting of IFNγ, anti-IL-10 and TLR3 agonist poly-IC in subcutaneous tumor models." (PMID 39551601, 2024). "TLR3 staining patterns (tumor edge or interior) and intensity (0—none; 1—faint; 2—moderate; and 3—intense staining) in each tumor sample were scored by two blinded investigators." (PMID 39348939, 2024). "The enhanced TLR3 response stimulates an amplified IFN type I response, resulting in a significant lymphocyte infiltration, shifting the ratio to favor CD8+ effector cells over immunosuppressive CD8+ T-regulatory (Treg) cells within the tumor microenvironment." (PMID 38256021, 2024). "BCCs, regardless of histological subtype, had strong, uniform TLR3 protein expression throughout the tumor." (PMID 39348939, 2024). "We have shown that the combined use of toll-like receptor 3 (TLR3) ligands with interferon-α (chemokine modulation: CKM) is able to enrich the tumor with CD8+ T cells, while not increasing immunosuppressive cells." (PMID 39072334, 2024). "The role of TLR3 in boosting IFN-β levels is particularly relevant, as IFN-β not only aids in viral clearance but also supports an immune-permissive tumor environment by increasing antigen presentation and stimulating CD8+ T cell responses, which are essential for effective chemotherapy." (PMID 39791120, 2024). "TLR3, a crucial pattern recognition receptor in immune responses against HPV and cervical intra-epithelial neoplasia, enhances anti-tumor immunity but can also inadvertently promote tumor growth through promoting pro-inflammatory cytokine production." (PMID 38835778, 2024). "In vertebrates, the interaction between HMGB3 and TLR3, TLR7, and TLR9, which occurs on the membrane, leads to upregulation of the production of ROS and activation of NF-kB signaling, which ultimately regulates tumor growth and metastasis." (PMID 39062899, 2024). "CXCL10, P2RX7, TLR3, and TLR4 were significantly upregulated in IS2 tumours in the TCGA cohort, whereas ANXA1, CXCL10, FPR1, IFNAR2, P2RX7, and TLR4 showed significantly higher expression levels in IS4 tumours in the GEO cohort." (PMID 36851274, 2023). "Rintatolimod (Poly(I:C12U)) is considered as an inducer of inflammation acting mainly through TLR3 but has not been reported to induce tumor cell death." (PMID 37275475, 2023). "There is a growing body of preclinical evidence that agonists targeting TLR3, TLR5, TLR7/8, or TLR9 in combination with RT may lead to enhanced anti-tumor immunity." (PMID 37112730, 2023). "Last but not least, we verified the TLR3 mRNA expression levels between tumor tissues and paracancerous nontumor tissues of early KIRC patients." (PMID 36419829, 2022). "We have every reason to speculate that TLR3 affects the prognosis of KIRC, LGG and PAAD by affecting tumor immune microenvironment, although TLR3 is also likely to influence the prognosis of patients through other factors." (PMID 36419829, 2022). "However, low expression of the TLR3-TICAM1 pathway reduces the dendritic cells and increases M2 macrophages, thereby weakening immune responses to tumor cells and stimulating tumor cells to progress." (PMID 35933370, 2022). "Moreover, the therapeutic effect of radiotherapy in combination with poly-IC was shown to enhance radiation-sensitivity via TNF-α produced by intra-tumor macrophages and CTL induced by TLR3-positive DC." (PMID 35413927, 2022). "TLR3-TICAM1 signaling is an inflammation response pathway, and in WT, downregulated TICAM1 may prevent inflammation responses to tumor cells." (PMID 35933370, 2022). "For example, TLR3 stimulation could induce OXPHOS to be converted into glycolysis in tumor cells, supporting the tumor’s adaptation to hypoxia." (PMID 34638609, 2021).
tumor (continued). "One report described the simultaneous administration of cell-based immunotherapy with a TLR3 agonist, where treatment with peptide-pulsed DCs plus poly-ICLC was tolerated and induced a detectable tumor-specific T cell response in patients with pancreatic cancer." (PMID 34124272, 2021). "At the pathway level, while several genes involved in TLR signaling (TLR3, TLR4, IRAK1) co-varied positively with Methylibium and Enhydrobacter in healthy control networks, these associations were not identified in tumor networks." (PMID 33863341, 2021). "TLR3 agonist ARNAX can initiate CD8+ T without the production of cytokines, cause tumor regression in mice without systemic inflammation, and can enhance the efficacy of PD-1/PD-L1 blockade." (PMID 33732237, 2021). "SLA archaeosomes combined with the TLR3 agonist Poly(I:C) comprise a powerful adjuvant system for SLP-based vaccines, inducing high levels of antigen-specific T cells that are functional and efficacious in a therapeutic tumor model." (PMID 33673382, 2021). "cGAS−/−, STING−/− and TLR3−/− mice showed similar tumor reduction as C57BL/6 WT animals after three treatments with intratumoral BCG, discarding the importance of these receptors in BCG-induced tumor regression." (PMID 34341449, 2021). "Interestingly, TLR3 agonist ARNAX has been demonstrated to induce activation and infiltration of tumor-specific cytotoxic T lymphocytes and relieve the resistance to PD-L1 blockade without systemic production of cytokines or IFNs." (PMID 33147700, 2020). "To evaluate whether the direct effect on A20 tumor cells could also be induced by other TLR agonists currently used for intratumoral therapy, we treated A20 cells side-by-side with the TLR3 agonist poly I:C, TLR9 agonist ODN2006, or GLA-AF." (PMID 32974162, 2020). "Of significance to the aberrant immune responses observed in ME/CFS is a recent seminal observation in cancer that rintatolimod increases the ratio of Teff/Treg cells in the tumor microenvironment, in contrast to non-restricted dsRNA TLR3 agonists." (PMID 33119613, 2020). "Therefore, inhibition of LSD1 increases the accumulation of dsRNA, which is sensed by MDA5 and TLR3, and then activates the expression of IFNs and MHC-I expression in tumor cells." (PMID 33214545, 2020). "In fact, in these mice treatment with either CTX or combined CTX + anti-PDL did not induce any increase in circulating tumor specific CD8+ T cells meaning that TLR-3 signaling in tumor cells is crucially required for the immunostimulatory effect of CTX." (PMID 32290265, 2020). "Importantly, combined TLR3/CD40 stimulation was needed to increase the frequency of CD8+ TILs in AT-3 tumors, and tumor-specific Tet+ CD8+ T cells in the PB and 4T1 tumors." (PMID 33110069, 2020). "Intratumoral Flt3L administration either with RT or with CD40/TLR3 stimulation did not alter tumor growth or survival; however, it did so only when combined with both procedures simultaneously." (PMID 33110069, 2020). "Additional weekly TLR3/CD40 stimulation once or twice following ISIM did not improve tumor response compared to mice treated with ISIM once in AT-3 tumor-bearing mice." (PMID 33110069, 2020). "Poly-ICLC (Hiltonol) is a TLR3 agonist comprised of synthetic dsRNA, which stimulates the production of pro-inflammatory cytokines and IFN-γ; however, there are mixed results regarding TLR3’s role in tumor cell intrinsic phenotypes." (PMID 32937885, 2020). "Patients with TLR3-positive immune infiltrating cells, but not tumor cells showed a worse prognosis compared with all other patients." (PMID 31582772, 2019). "For targeted delivery of TLR3 agonist to tumor cells we sought to employ this platform technology and to couple biotinylated nucleic acid-based TLR agonists, in particular dsRNA, to tumor-specific antibodies via consecutive bio-conjugation to neutravidin." (PMID 30824859, 2019). "Tumor antigen crosspriming is known to be up-regulated by type I IFN and TLR3 function." (PMID 31046839, 2019).
tumor (continued). "Most endothelial cells were negative for caspase in tumours of WT and Tlr3/7/9−/− mice, making substantial endothelial caspase-mediated cell death during tumour rejection unlikely." (PMID 28300057, 2017). "We can also suggest that EBV/EBER-driven TLR3 signaling may favor antiviral type I IFN production and inflammatory responses, which contribute to create a tumor microenvironment favoring the recruitment of peripheral B cells." (PMID 29221139, 2017). "Interestingly, stimulation through TLR-3, -4, and -7 has previously been reported to synergize with CD47 blockade on tumor cells by increasing secretion and cell-surface exposure of calreticulin on macrophages in a Btk-dependent manner." (PMID 29084248, 2017). "Toll-like receptor-3 (TLR3), a member of the pathogen recognition receptor family, has been reported to activate immune response and to exhibit pro-apoptotic activity against some tumor cells." (PMID 28790362, 2017). "Tumor collapse could result in the release of RNA, which may evoke EMT via TLR3, resulting in greater invasion or metastasis by the self-secretion of IL-8 from the tumor." (PMID 28438134, 2017). "Interestingly, activation of multiple TLRs using a combination of TLR3, TLR4, and TLR7 ligands resulted in tumor rejection in 50% of mice in a B16-OVA tumor model with poor immunogenicity, increasing innate immunity and CD8+ and CD4+ T-cell responses." (PMID 29190881, 2017). "Moreover, some researches showed that apoptotic cell-derived RNA and DNA can activate MSCs and other immune cells through TLRs such as TLR-3 and provides a feed forward reaction, leading to the increase in TRAIL expression and subsequent tumor suppression." (PMID 27329316, 2016). "However, a combined PD-1/PD-L1 blockade with a TLR3 agonist resulted in an increase of CD8 T-cell effectors and anti-tumor responses in a murine melanoma model." (PMID 26379664, 2015). "Here, we extended our studies to assess whether monotherapy with the GMP-grade TLR3 agonist poly-ICLC, could restrict tumor growth in both transplanted and spontaneous models of liver tumors." (PMID 26287667, 2015). "TLR3 expression in the cytoplasm or membrane was detected in 58.8% (50/85), 67.1% (57/85), and 80.0% (24/30) of the tumor, normal, and non-HCC sections, respectively." (PMID 25884709, 2015). "However, evidence of TLR3 and TLR7 tumor-promotion has been reported for other cancers such as in lung, pancreas, and liver." (PMID 25411122, 2014). "Finally, a DC based vaccine delivered with TLR3 and TLR 2 provided enhanced protection to mice challenged with tumor." (PMID 24982761, 2014). "Moreover, IL-27 increases TLR3 expression and therefore the combination of IL-27 and poly(I:C) cooperatively enhances TRAIL expression and inhibits tumor growth." (PMID 24155891, 2013). "In contrast, TLR3 staining was absent or weaker in stromal cells and tumor infiltrating lymphocytes." (PMID 23198710, 2012). "These included transcription factor EGR1 which is reported to have tumor suppressor properties, genes involved in lymphocyte activation and differentiation such as BCL6, CD4 and SMAD3 and genes TLR3 and TIRAP that are part of the toll-like receptor signaling pathway." (PMID 23072359, 2012). "Although blockade of TLR3 markedly reduced apoptosis of tumor cells treated by poly I:C/CHX, we can not completely exclude the possibility that RIG-I/MDA5 contributed to the recognition of poly I:C internalized by endocytosis." (PMID 18199340, 2008). "Therefore, we are not exploring only the role of TLR3 in DAMP-mediated CSCs’ contribution to tumor progression, but possibly also other TLRs as well." (PMID 40647457, 2025).
tumor (continued). "This selective activation suggests targeting TLR3/TRAF3/IRF3 without activating NFκB could improve cancer immunotherapy by boosting anti-tumor immunity while minimizing immune suppression." (PMID 39949780, 2025). "In particular, the expression values of TLR-2, TLR-3, TLR-4, and TLR-9 on CD3-CD56+ cells increased proportionally with the tumor stage, suggesting that these receptors may be functional as diagnostic and prognostic biomarkers in assessing the progression of GC." (PMID 39594809, 2024). "The same study further analyzed the response of one cell line (OC2) to TLR3 stimulation, and observed an increase in the phosphorylation of IRF3 and IκB and a resulting induction in the secretion of IL6 and CCL5, which are closely related to tumor aggressiveness." (PMID 37112730, 2023). "Although there was a slight decrease in the efficacy of poly(I:C) in tumors derived from TLR3 knockout (KO) cancer cells, this was not significant (p = 0.08), suggesting that TLR3 expression on tumor cells is not sufficient for the anti-cancer effect of poly(I:C)." (PMID 37467718, 2023). "We believe that unlike LPS that works via TLR4, DAMPs & PAMPs present in tumor cell lysate can induce DC activations through multiple signaling mechanisms (TLR3, TLR4, RAGE, etc.)on DCs, thereby generating dramatic different immunoactivities with β2AR activation vs LPS alone." (PMID 37006295, 2023). "Mechanistically, the absence of TLR3 prevents cell apoptosis and enhances tumor progression." (PMID 37020586, 2023). "Similarly, polyinosinic-polycytidylic acid polylysine carboxymethylcellulose (poly-ICLC)—a synthetic Poly(I:C) (TLR3 and MDA5 agonists)—can induce immune response mediated by tumor-specific NK, CTL, and NK-T cells, leading to the robust elicitation of multiple IFNs." (PMID 35745800, 2022). "This non-inflammatory TLR3 agonist was shown to synergize with PD-L1 blockade in tumor eradication in immunocompetent hosts to overcome PD-1/PD-L1 resistance and provide long-term protection from tumor relapse." (PMID 34006895, 2021). "In this work, a middle-out strategy was followed to develop a model describing the antitumor efficacy of different immune-modulator combinations, including an antigen, a toll-like receptor-3 agonist, and an immune checkpoint inhibitor in mice treated with non-inflamed tumor cells." (PMID 34680196, 2021). "Indeed, co-delivery of polyIC-R837@mPEG-PL-OA-IONPs (as TLR3-7 agonists) and OVA@mPEG-PL-OA-IONPs (as antigen) delayed tumor growth in OVA-expressing B16-bearing animals and led to tumor-free survival in some individuals, probably through an enhanced agonist effect on TLR signaling." (PMID 34177955, 2021). "Tumor size of mice treated with TC-1/A9 non-inflamed tumors and the drug effects of an antigen, a toll-like receptor-3 agonist (PIC), and an immune checkpoint inhibitor (anti-programmed cell death 1 antibody) were modeled using Monolix and following a middle-out strategy." (PMID 34680196, 2021). "In addition, several preclinical studies have demonstrated that agonists of the TLRs (TLR3, TLR7/8 and TLR9) in macrophages may enhance anti-tumor treatment efficacy by polarizing M0 macrophages into Th1 and M1-like TAMs and inhibiting tumor progression." (PMID 33323552, 2020). "However, critical observation of previously published IHC results show nuclear positivity of TLR3 in a certain percentage of tumor cells, but no precise interpretation of such pattern is available up-to-date." (PMID 33147700, 2020). "In our study, TLR family expression, specifically TLR1, TLR3, TLR4, and TLR6, was upregulated in BD3 tumors in comparison with low-grade budding tumors (both in patient and PDX tumors) suggesting the presence of TLR-mediated alterations in the tumor invasive front." (PMID 32719800, 2020).
tumor (continued). "To investigate the functional phenotype of TLR3-expressing macrophages, we analyzed by IHC analysis the expression of CD163, marker of M2 macrophages reported to function in immune suppression and also tumor progression, on a portion of NSCLC specimens whose material were available." (PMID 31582772, 2019). "The lack of significance for TLR3-i could be explained by the lower number of total immune cells in the tumor versus the surrounding stroma,23,24." (PMID 31582772, 2019). "In the last years, the pharmacological targeting of TLR3, TLR7, TRL8, and TLR9 located in the endosomal compartment of antigen-presenting cells, such as macrophages, has been prioritized versus extracellular TLRs, presumably due to their higher capacity to trigger anti-tumor immune responses." (PMID 31878087, 2019). "Considering that induction of inflammatory pathways is a general outcome of TLR3 activation, the fact that TLR3-mediated apoptosis occurs in human tumor cell lines but not in their normal counterparts indicates that sensitivity is acquired during cell transformation." (PMID 30158588, 2018). "The systemic administration of immunostimulatory agents, such as the synthetic TLR3 agonist poly(I:C) injected intraperitoneally (i.p.)or the oncolytic virus VSVΔ51 administered intravenously (i.v.), induced the production of cytokine TNF-α in the serum and brain of non-tumour bearing mice." (PMID 28198370, 2017). "In mice injected with TLR3 down regulated HCT116 cells, the mean (+/- SEM) tumor weight of the mice treated with reovirus was 115 (+/- 8) mg, and was significantly lower than the tumor growth in the untreated mice, 1698 (+/- 84) mg (p = 0.000081; 93.2% reduction)." (PMID 28422714, 2017). "In contrast, only one out of six Tlr3/9−/− mice could reject the tumour and only two single KO mice did not develop a tumour after 3–4 weeks." (PMID 28300057, 2017). "Even in epithelial and tumor cells, stimulation of TLR3 does not promote cell growth or inflammation, which may be attributable to suppression of c-Myc." (PMID 29041928, 2017). "Hence, despite an initial growth retardation after TLR3 activation, the acquisition of CSC phenotypes in the remaining tumor cells could engender a stronger and more robust ‘second wave' of tumor growth (greater than 100-fold)." (PMID 25257174, 2015). "Reovirus-induced innate immune responses via TLR3 might be inhibited by the cathepsin B inhibitor, although siRNA-mediated knockdown of TLR3 did not apparently decrease mRNA levels of IFN-β and Noxa following treatment with reovirus in tumor cells." (PMID 25866783, 2015). "This resulted in a failure to establish an anti-tumor immune response, suggesting that TLR3-induced PD-L1 expression on DCs may act as a negative regulator of CD8+ T cells expansion." (PMID 24348481, 2013). "Likewise, interferon response genes (including TLR3, MX1, RSAD2, IFI44, IFI27, IFIT1, and IFIT3), and chemokine genes (including CCL7, CXCL10, CXCR1, and CCL25) were significantly increased in PM-treated MM tumor tissues, whereas panobinostat showed minimal effects at equivalent doses." (PMID 40562746, 2025). "In addition, tumor cells without TLR3 have been shown to be more resistant to chemotherapy." (PMID 38738791, 2024). "TLR3, TLR4 and TLR7 are upregulated in certain types of tumour cells, and their expression patterns are associated with tumour progression, suggesting that the innate immunity‐related factors may function as tumour promotors rather than suppressor." (PMID 35050535, 2022). "Interestingly, we also compared their expression levels between tumor and normal tissues and found that the expressional changes were complex, especially significantly upregulated genes (CDKN2A, MYCN, PLK1, and TERT) and some downregulated signatures (AXL, ID1, and TLR3)." (PMID 35754848, 2022).